KCTD7 (potassium channel tetramerization domain containing 7)
Description:
Substrate-specific adapter of a BCR (BTB-CUL3-RBX1) E3 ubiquitin ligase complex that mediates the ubiquitination of multiple substrates, leading to either their proteasomal or lysosomal degradation, or modulating their activity through non-degradative ubiquitination. Regulates voltage-gated potassium channels, thereby modulating hyperpolarizing potassium currents in neurons and inducing potassium-dependent membrane hyperpolarization. Also regulates the neuronal glutamine transporter SLC38A2/SAT2, influencing neurotransmitter precursor availability. Regulates calpain activity via atypical, non-degradative ubiquitination by mediating ubiquitination of CAPN1 via 'Lys6'-, 'Lys27'-, 'Lys29'-, and 'Lys63'-linked chains, and CAPN2 via 'Lys6'-linked chains, thereby preventing calpain autolysis. Promotes lysosomal enzyme trafficking and maintains lysosomal function by acting as an endogenous regulator of CLN5, enhancing its ubiquitination and proteasomal degradation.
Synonyms: FLJ32069; EPM3; CLN14
Tractability: Antibody: its Gene Ontology location is reachable by antibodies, with high confidence; UniProt places it where antibodies can reach, with medium confidence.
Gene: Protein-coding gene on chromosome 7 (66,628,881 to 66,649,067, forward strand). Ensembl gene ENSG00000243335.
Subcellular location: Cell membrane; Cytoplasm
Pathways (Reactome):
Immune System: Antigen processing: Ubiquitination & Proteasome degradation
Metabolism of proteins: Neddylation
Gene Ontology:
Molecular function: protein binding; identical protein binding
Biological process: intracellular glutamate homeostasis; membrane hyperpolarization; intracellular potassium ion homeostasis; protein homooligomerization
Cellular component: cytoplasm; plasma membrane; cytosol
Genetic constraint (gnomAD): Loss-of-function variants: 15 observed, 25.61 expected, observed/expected ratio (o/e) 0.59, 90% interval 0.39 to 0.9. The upper end of that interval is the gene's LOEUF score, 0.9, which puts it in group 3 of 6, group 1 being the genes least tolerant of losing a copy. Missense variants: 299 observed, 383.01 expected, observed/expected ratio (o/e) 0.78, 90% interval 0.71 to 0.86. Synonymous variants: 159 observed, 155.51 expected, observed/expected ratio (o/e) 1.02, 90% interval 0.9 to 1.17.
Gene-disease validity (ClinGen):
ClinGen rates the evidence that KCTD7 causes each of these diseases.
progressive myoclonus epilepsy (autosomal recessive): Definitive. A rare group of disorders characterized by the development of myoclonic and tonic-clonic epileptic seizures associated with progressive degeneration of the nervous system.
Homologues: Orthologues: chimpanzee KCTD7 (100% identical), guinea pig KCTD7 (98% identical), mouse Kctd7 (98% identical), pig KCTD7 (98% identical), rat Kctd7 (97% identical), macaque KCTD7 (88% identical), tropical clawed frog KCTD7 (78% identical), zebrafish kctd7 (74% identical), Drosophila melanogaster twz (21% identical), Caenorhabditis elegans F32B4.5 (10% identical). Paralogues in human: KCTD14 (27% identical), KCTD6 (24% identical), KCTD15 (22% identical), KCTD8 (21% identical), KCTD1 (21% identical), KCTD11 (21% identical), KCTD16 (20% identical), KCTD19 (20% identical), KCTD21 (19% identical), KCTD12 (19% identical), KCNRG (17% identical), KCTD18 (16% identical), and 1 more.
Diseases named in the same sentence as KCTD7 in open-access papers:
KCTD7 is named in the same sentence as 35 diseases in open-access papers, as found by Europe PMC text mining. Sharing a sentence is not in itself a finding about the gene and the disease. The quoted sentences say what the papers report.
Progressive myoclonic epilepsy (12 papers, 2010 to 2025). "Biallelic variants in KCTD7 have been associated with progressive myoclonic epilepsy (PME), a rare autosomal recessive disorder characterized by early-onset epilepsy, cognitive decline, myoclonus, and ataxia." (PMID 41311698, 2025). "The c.334C > T (p.Arg112Cys) variant had previously been reported as a homozygous variant in a patient with KCTD7-related progressive myoclonic epilepsy." (PMID 41311698, 2025). "Since the identification of KCTD7 as an autosomal recessive, progressive myoclonus epilepsy-associated gene over 15 years ago, relatively little progress has been made toward understanding the pathophysiology linking KCTD7 to human neurodevelopmental disease." (PMID 35972048, 2022). "Mutations in CLN14/KCTD7 cause three different diseases classed as progressive myoclonic epilepsy (PME), and in rarer cases PME accompanied by vision loss and lysosomal storage and termed an NCL." (PMID 34733232, 2021). "Most homozygous and compound heterozygous mutations in the KCTD7 have been described in patients with progressive myoclonic epilepsy (PME) who have normal intracellular accumulation of storage material." (PMID 32412666, 2020). "Mutations in the potassium channel tetramerization domain-containing protein 7 (KCTD7) have been extensively linked to progressive myoclonic epilepsy." (PMID 30651094, 2019). "Biallelic KCTD7 mutations define the diagnosis of EPM3 (progressive myoclonic epilepsy-3), a severe neurodegenerative disorder with onset in early childhood." (PMID 30142151, 2018). "Candidate genes on CFA 6 based on human studies would be KCTD7, a potassium channel associated with progressive myoclonic epilepsy and EIM." (PMID 20441595, 2010). "For example, a homozygous mutation (R99X) in exon 2 of KCTD7 has been described in progressive myoclonic epilepsy (PME)." (PMID 24268103, 2013). "Nonsense as well as missense variants in KCTD7 cause progressive myoclonic epilepsy with or without intracellular inclusions in an autosomal recessive pattern." (PMID 37485353, 2023). "Moreover, homozygous mutations in the KCTD7 gene have been reported to cause a subtype of NCL discovered in two siblings in a Mexican family who presented with infantile-onset, progressive myoclonic epilepsy, cognitive impairment, loss of vision, motor regression, and premature death." (PMID 30651094, 2019).
epilepsy (7 papers, 2018 to 2023). A brain disorder characterized by episodes of abnormally increased neuronal discharge resulting in transient episodes of sensory or motor neurological dysfunction, or psychic dysfunction. "Here we show that calpains are regulated by KCTD7, a cytosolic protein of previously uncharacterized function whose pathogenic mutations result in epilepsy, progressive ataxia, and severe neurocognitive deterioration." (PMID 36964131, 2023). "Pathogenic KCTD7 mutations cause epilepsy, progressive ataxia, and severe neurocognitive deterioration." (PMID 36964131, 2023). "Together, these data indicate that Kctd7 function is required to prevent seizures and deficits in motor control, and add KCTD7-PME to the increasing number of gene defects linked to disordered brain microvasculature in epilepsy." (PMID 35972048, 2022). "We also identified intense Kctd7 expression at this time point in the entorhinal cortex and the subthalamic nucleus, regions linked to epilepsy and focal motor phenotypes." (PMID 35972048, 2022). "Taken together, these results define a new model for KCTD7-associated epilepsy and identify Kctd7 as a modulator of neuron survival and excitability linked to microvascular alterations in vulnerable regions." (PMID 35972048, 2022). "Four patients with RE carried CNVs that disrupted genes known to cause other epilepsies; KCTD7, ARHGEF4, ARHGEF15 and CACNA2D1, expanding the phenotypes associated with these genes." (PMID 29789371, 2018). "KCTD7 deficiency is an example of a shared genetic pathway involving the brain (epilepsy) and cerebellum (degeneration of Purkinje cells) and could be used as a possible model for research on this topic." (PMID 36294502, 2022). "Five patients with RE carried a rare CNV that disrupted genes associated with other epilepsies (KCTD7, ARHGEF15, CACNA2D1, GRIN2A and ARHGEF4), and 17 cases carried CNVs that disrupted genes associated with other neurological conditions or that are involved in neuronal signalling/development." (PMID 29789371, 2018). "Animal models of KCTD7-related disease are lacking, and little is known regarding how KCTD7 protein defects lead to epilepsy and cognitive dysfunction." (PMID 35972048, 2022).
Ataxia (5 papers, 2022 to 2025). Ataxia refers to impaired coordination of voluntary muscle movement. "In addition, defects in various potassium channels (KCNC1, KCTD7) have been associated with PMEs such as myoclonus epilepsy and ataxia due to potassium channel mutations (MEAK) and KCTD7-related PME (EPM3)." (PMID 39156922, 2024). "Mutations in the KCTD7 gene cause a spectrum of progressive neurodegenerative phenotypes characterized by ataxia and psychomotor decline/motor incoordination preceded in some (but not all) cases by intractable myoclonic seizures after several months of normal development." (PMID 36964131, 2023). "Human KCTD7 patients display pronounced motor defects that can manifest as ataxia, tremors and dyskinesia." (PMID 35972048, 2022). "Biallelic KCTD7 variants are a known cause of autosomal recessive progressive myoclonic epilepsy type 3 (PME3), characterized by early-onset drug-resistant epilepsy, myoclonic and generalized seizures, progressive cognitive decline, and ataxia." (PMID 41311698, 2025). "Unlike most SCA genes, KCTD7 mutations promote an early onset of ataxia." (PMID 35972048, 2022). "The findings in our family demonstrate the typical course of KCTD7-related PME, with early-onset ataxia, refractory epilepsy, cognitive regression, ESES on EEG, and minimal MRI findings." (PMID 41311698, 2025).
neuronal ceroid lipofuscinosis (4 papers, 2014 to 2025). "KCTD7 encodes a member of the potassium channel tetramerization protein and pathogenic variants in this gene cause neurodegenerative disorders ranging from early onset intractable myoclonic epilepsy and developmental regression to neuronal ceroid lipofuscinosis." (PMID 40399560, 2025).
myoclonic epilepsy (3 papers, 2024 to 2025). A group of epilepsy syndromes in which myoclonic seizures are a prominent feature. "Additionally, a case of OMS with myoclonic epilepsy revealed the presence of a heterozygous missense mutation and a large deletion in the potassium channel tetramerization domain containing 7 (KCTD7) has been reported." (PMID 38737300, 2024).
glioblastoma (2 papers, 2022 to 2024). The most malignant astrocytic tumor (WHO grade IV). "Only two previous literatures derived from clinical data mining showed that the alternative splicing of KCTD7 had a prognostic value in glioblastoma and lung adenocarcinoma." (PMID 38438714, 2024).
progressive myoclonic epilepsy type 3 (2 papers, 2022 to 2025). Any progressive myoclonic epilepsy in which the cause of the disease is a mutation in the KCTD7 gene. "Patients with KCTD7 mutations were first diagnosed with progressive myoclonic epilepsy type 3 (EPM3)." (PMID 35921411, 2022). "Mutation in KCTD7 is associated with progressive myoclonic epilepsy type 3 (EPM3)." (PMID 39925015, 2025).
autism (1 paper, 2019). Persistent deficits in social interaction and communication and interaction as well as a markedly restricted repertoire of activity and interest as well as repetitive patterns of behavior. "Varying levels of evidence support their roles in neurocognitive disorders (KCTD3), neurodevelopmental disease (KCTD7), bipolar disorder (KCTD12), autism and schizophrenia (KCTD13), movement disorders (KCTD17), cancer (KCTD11), and obesity (KCTD15)." (PMID 31197948, 2019).
channelopathy (1 paper, 2022). Channelopathies are a group of diseases caused by the dysfunction of ion channel subunits or their interacting proteins. "The underlying channelopathy pathway accounted for 46.7% (7/15) of the monogenic variants, including ion channel genes (SCN1A, KCTD7, KCNC1, CACNA1A, KCNMA1) and ligand-gated ion channel genes (GABRA1, GABRG2)." (PMID 36034301, 2022).
Williams-Beuren syndrome (1 paper, 2015). "Such functions are also known for the genes that are ECpiC loci, such as the oncogenic transcription factors ABL2 and ELK4, the miRNA effector AGO2, and TBL2 and KCTD7 genes that are in the deleted locus of Williams-Beuren syndrome patients, which display developmental defects." (PMID 26588211, 2015).
cancer (4 papers, 2019 to 2024). A tumor composed of atypical neoplastic, often pleomorphic cells that invade other tissues. "The identification of the function of KCTD7 as a calpain adapter sheds light on the molecular pathogenesis of KCTD7-associated disease and suggests novel therapeutic avenues to mitigate the pathological effects of calpain hyperactivity in neurodegenerative disease and cancer." (PMID 36964131, 2023). "Our analysis results showed that both KCTD7 and 15 expression levels were downregulated in CRC tissues as compared to the non-cancer tissues." (PMID 38438714, 2024).
neurological disease (2 papers, 2022 to 2023). "These included genes that encode a component of the SCF ubiquitination complex (FBXO31), an enzyme involved in fatty acid oxidation (HADH) and a member of the KCTD family (KCTD7), mutations in which have been linked to several neurological disorders." (PMID 37818590, 2023). "Even less is known about the precise molecular and cellular biology underlying KCTD7-driven human pathology, and no mouse models of the neurological disease have as yet been reported, apart from our recent study of Kctd7-linked retinal function and vascular defects." (PMID 35972048, 2022).
genetic diseases (1 paper, 2022). "The biological functions of KCTD7, the gene mutated in the two rare genetic diseases, CLN14 and EPM3, remain elusive." (PMID 35921411, 2022).
KCTD7 also shares sentences with these, for which no sentence is quoted: early-onset epilepsy (2 papers); movement disorder (2); bipolar disorder (1); cardiac hypertrophy (1); cerebellar degeneration (1); Cognitive impairment (1); Dyskinesia (1); Dystonia (1); encephalopathies (1); frontotemporal dementia (1); Kaya-Barakat-Masson syndrome (1); Myoclonus (1); myoclonus epilepsy (1); neuroblastoma (1); neurodegenerative disease (1); Obesity (1); opsoclonus-myoclonus syndrome (1); progressive cognitive decline (1); progressive neurodegenerative disorder (1); schizophrenia (1); Spastic paraplegia (1); Tremor (1).